SMAD2 (SMAD family member 2)
Diseases named in the same sentence as SMAD2 in open-access papers (continued):
Sharing a sentence is not in itself a finding about the gene and the disease.
pulmonary fibrosis (continued). "Mechanistically, GSR disruption boosts intracellular ROS levels and then activates the TGF-β/Smad2 pathway, shedding light on the key mechanism in oxidative stress-induced pulmonary fibrosis and providing new understanding for managing age-related diseases." (PMID 40723921, 2025). "To further elucidate the mechanisms underlying the anti-fibrotic effects of LP03, we examined its impact on the TGF-β1/Smad2/3 signaling pathway in a BLM-induced pulmonary fibrosis mouse model." (PMID 40994978, 2025). "For example, Bufei huoxue capsule, as a TCM formulation, can alleviate BLM-induced pulmonary fibrosis in mice by inhibiting the TGF-β/Smad2/3 signaling pathway." (PMID 38263193, 2024). "Lentiviral expression of miR-18a-5p in bleomycin mice presented lowered levels of phosphorylated Smad2/3 and a reduction in pulmonary fibrosis." (PMID 38920689, 2024). "We conclude that BIC reduces SiO2-induced pulmonary fibrosis by inhibiting the inflammatory fibrotic responses in silicosis via the TGF-β1/SMAD2/3 and JAK2/STAT3 signaling pathways." (PMID 39060930, 2024). "Another study in a mouse model of silicosis and isolated murine alveolar macrophages showed that quercetin treatment alleviated pulmonary fibrosis by inhibiting macrophage-to-myofibroblast transition through interference in the TGF-β-Smad2/3 signaling pathway." (PMID 38474385, 2024). "Recent research shows that periostin enhances the TGF-β/Smad2/3 signaling pathway via integrin αVβ3/αVβ5 in lung fibroblasts, contributing to pulmonary fibrosis development." (PMID 38370408, 2024). "Then, the detection of phosphorylated Smad2/3 confirmed the activation of the Smad pathway, which corresponds with the severity of lung fibrosis." (PMID 40303164, 2024). "Collectively, these data suggest that theophylline has an anti-fibrotic effect on BLM-induced pulmonary fibrosis by inhibiting the TGF-β/Akt/Smad2/3 pathway." (PMID 36674533, 2023). "As sustained phosphorylation of SMAD2 protein is reported in TGF-β-induced pulmonary fibrosis, we also measured the protein level of phosphorylated SMAD2 in the lung cell lysates." (PMID 37051024, 2023). "Recent evidence suggests that resveratrol (RSV) attenuates excessive inflammation and pulmonary fibrosis by inhibiting the TGF-β/Smad2/3/4, NF-κB, and JAK/STAT signal transduction pathways and overactivation of immune cells." (PMID 37089962, 2023). "Further investigation revealed that inhibition of ADRB2 impedes lung fibrosis by reducing TGF-β/SMAD signaling activity through the acceleration of phos-SMAD2/3 proteasome degradation." (PMID 37923730, 2023). "LRG1 has also been identified as a promoter of lung fibrosis through the modulation of TGF-β-induced SMAD2 phosphorylation and the activation of profibrotic responses in fibroblasts." (PMID 37569820, 2023). "The TGF-β1/Smad2 signaling pathway is an important regulatory pathway for pulmonary fibrosis and PAH, and it is involved in many cardiovascular diseases." (PMID 36611616, 2022). "We also provide in vivo and in vitro evidence that NecroX-5 attenuated pulmonary fibrosis and the TGFβ1/Smad2/3-mediated EMT process." (PMID 35596212, 2022). "Activation of the TGF-β1/Smad2 signaling pathway resulted in a large deposition of the extracellular matrix components, such as collagen fibers, which induced pulmonary fibrosis." (PMID 36611616, 2022). "Our results showed that the TGF-β1/Smad2 signaling pathway was involved in broiler PAH by regulating pulmonary fibrosis and pulmonary arteriole remodeling." (PMID 36611616, 2022). "The downstream signal of TGF-β1 is significantly activated in both BLM-injured mice and TGF-β1-stimulated cells, as indicated by increased phosphorylation of Smad2/3, which is an essential mechanism in the pathogenesis of pulmonary fibrosis." (PMID 35172837, 2022).
pulmonary fibrosis (continued). "This suggests that NecroX-5 ameliorated BLM-induced pulmonary fibrosis by inhibiting the TGF-β1/Smad2/3- mediated EMT process, which is dependent on the inhibition of NLRP3 inflammasomes." (PMID 35596212, 2022). "A decrease in Let-7d expression induces an increase in COL3A1 and SMAD2 expression, which are involved in the development of pulmonary fibrosis." (PMID 36012303, 2022). "TGF-β and Smad2/3 were significantly upregulated in the model mice, indicating that TGF-β/Smad2/3 pathway is involved in BLM-induced pulmonary fibrosis." (PMID 35685407, 2022). "To investigate the signaling pathways pivotal for IL-11–driven pulmonary fibrosis, we assessed the activation status of SMAD2, ERK, and STAT3 by Western blotting of lung homogenates from the PBS-treated group, siIL11@PPGC NP–treated group, or healthy controls." (PMID 35731866, 2022). "Smad2/3-mediated EMT of alveolar epithelial cells is involved in the pathogenesis of BLM-induced lung fibrosis." (PMID 33952237, 2021). "Our results showed that TUDCA suppressed pulmonary TGF-β/Smad2/3-mediated EMT in the process of BLM-induced lung fibrosis." (PMID 33952237, 2021). "Some studies reported that miRNAs, including miR-18a-5p, miR-153, and miR-1344, play anti-pulmonary fibrosis effects for targeting TGF-β receptors to inhibit downstream SMAD-2/3 expression." (PMID 34381815, 2021). "In this study, we have focused on protection effect of TUDCA pretreatment against TGF-β/Smad2/3-mediated EMT in the process of BLM-induced lung fibrosis." (PMID 33952237, 2021). "In animal model, inhibition of Sirt2 alleviated pulmonary fibrosis and reduced the phosphorylation of Smad2/3 induced by bleomycin." (PMID 34925016, 2021). "In contrast, miR-21 promotes the transduction of the TGF-β/SMAD-2/3 signaling pathway by directly targeting Smad7 to accelerate the process of pulmonary fibrosis." (PMID 34381815, 2021). "low level of SMAD7 in turn accelerated the phosphorylation of SMAD2/3 to promote the proliferation, migration and transition of fibroblasts, thereby exacerbating pulmonary fibrosis." (PMID 34093874, 2021). "The current study explored the effect of TUDCA on TGF-β/Smad2/3-mediated EMT in BLM-induced lung fibrosis." (PMID 33952237, 2021). "In summary, PFD not only alleviated pulmonary fibrosis of mice models caused by BLM, but also relieved TGF-β1-induced HLFs damage, which were mainly realized by regulating Wnt/GSK-3β/β-catenin and TGF-β1/Smad2/3 signaling pathways." (PMID 32448163, 2020). "Accumulating data have demonstrated that TGF-β/Smad2/3-mediated EMT plays an important role in the development of BLM-induced pulmonary fibrosis." (PMID 31775746, 2019). "For example, sunitinib, a small molecule kinase inhibitor, reduced phosphorylation of serine residues on SMAD2/3 and attenuated bleomycin‐induced pulmonary fibrosis in mice." (PMID 31482149, 2019). "Neutrophil elastase activated the Smad2/Smad3/α-SMA pathway to induce collagen deposition, while sivelestat abrogated the increased severity of pulmonary fibrosis caused by PM." (PMID 31905700, 2019). "In animal models of liver and lung fibrosis, UC-MSCs alleviated organ fibrosis and reduced the protein expression of phosphorylated Smad2 in whole organ protein extracts." (PMID 31547873, 2019). "A major process involved in pulmonary fibrosis development is the differentiation of fibroblasts into myofibroblasts, which requires Smad2/Smad3/α-SMA activation." (PMID 31905700, 2019). "Together, these data demonstrate the antifibrotic effect of tannic acid in bleomycin model of pulmonary fibrosis, which is accompanied by inhibition of Smad2 phosphorylation by tannic acid treatment." (PMID 31358001, 2019). "Recent studies from our group have found that inhibition of lncRNA PFRL prevents pulmonary fibrosis by disrupting the miR-26a/Smad2 loop, and lncRNA PFAL promotes lung fibrosis through CTGF by competitively binding miR-18a." (PMID 31273058, 2019).
pulmonary fibrosis (continued). "During the development of pulmonary fibrosis, phosphoinositide-3-kinase-protein kinase B (PI3K-Akt) signaling pathway caused activation of phosphorylation of Smad2 and deactivation of Smad3 (Zhao and Geverd, 2002)." (PMID 31611754, 2019). "Calpeptin also suppressed the activation of transforming growth factor β1 (TGFβ1)-Smad2/3 signaling pathway, which plays crucial role in lung fibrosis and EMT." (PMID 29666896, 2018). "In conclusion, this study is the first to show that ANP exerts anti-fibrotic and anti-inflammatory effects in BLM-induced pulmonary fibrosis via vascular endothelial cells, possibly by attenuating the phosphorylation of Smad2 in TGF-β signaling." (PMID 28049526, 2017). "Taken together, our data suggest that LRG promotes lung fibrosis by modulating TGF‐β‐induced Smad2 phosphorylation and activating profibrotic responses in fibroblasts." (PMID 29279415, 2017). "Our study of the lung fibrosis model suggests that LRG contributes to the activation of Smad2 signaling in the fibrotic lung." (PMID 29279415, 2017). "Proinflammatory cytokines TGF-β1 after lung injury contributes in the formation of pulmonary fibrosis through receptor mediated phosphorylation of Smad2 and Smad3." (PMID 28496412, 2017). "Here, we demonstrate that UCHL5 de-ubiquitinates and stabilizes Smad2 and Smad3, thereby promoting TGFβ-1 signaling and contributes to the pathogenesis of pulmonary fibrosis." (PMID 27604640, 2016). "But the role of UCHL5 in regulation of Smad2/Smad3 and pathogenesis of pulmonary fibrosis is still unclear." (PMID 27604640, 2016). "Transforming growth factor β-1 (TGFβ-1)-induced phosphorylation of transcription factors Smad2 and Smad3 plays a crucial role in the pathogenesis of idiopathic pulmonary fibrosis (IPF)." (PMID 27604640, 2016). "In conclusion, we demonstrate that UCHL5 de-ubiquitinates and stabilizes Smad2 and Smad3, promotes TGFβ signaling, and contributes to the pathogenesis of pulmonary fibrosis." (PMID 27604640, 2016). "This is the first study to identify that UCHL5 plays a pro-fibrotic role in the pathogenesis of pulmonary fibrosis through stabilization of Smad2/Smad3 and enhance in TGFβ-1 signaling in HLF and a murine model of pulmonary fibrosis." (PMID 27604640, 2016). "Our study demonstrated that Fstl l was upregulated through miR-21 expression after PQ challenge, resulting in increased Smad2/3 and p38MAPK phosphorylation and progressive PQ-induced pulmonary fibrosis." (PMID 26758514, 2016). "Administration of UCHL5 inhibitor, b-AP15, reduced the expression of FN, type I collagen, Smad2/Smad3, and the deposition of collagen in lung tissues in a bleomycin-induced model of pulmonary fibrosis." (PMID 27604640, 2016). "This likely reduced expression of profibrogenic genes and directly suppressed pulmonary fibrosis, thus protecting against miR-21-mediated injury and downregulating the major signalling transducer, Smad2/3." (PMID 26758514, 2016). "Phosphorylation of SMAD2 was detected in 3-week bleomycin-challenged mice, suggesting that TGFβ signaling contributes to the pathogenesis of bleomycin-induced pulmonary fibrosis." (PMID 27853171, 2016). "In our study, PQ markedly upregulated miR-21 expression, stimulated FSTL1 expression, facilitated TGF-β/Smad2/3 and p38MAPK signal transduction and induced pulmonary fibrosis." (PMID 26758514, 2016). "Next, we examined levels of UCHL5, Smad2 and Smad3 in murine lungs from a bleomycin-induced pulmonary fibrosis model." (PMID 27604640, 2016). "Our data indicate that miR-486-5p has an impact on the development of lung fibrosis partly by targeting SMAD2, which is one of downstream molecules of the TGF-β1 signaling pathway." (PMID 26370615, 2015). "AG administration dose-dependently reduced the phosphorylation of Smad2 and Smad3 protein in the bleomycin-induced pulmonary fibrosis (p < 0.05, p < 0.01)." (PMID 19552800, 2009).
pulmonary fibrosis (continued). "It has been reported that the expression of Smad3 mRNA was down-regulated at an early stage of inflammatory injury during bleomycin-induced pulmonary fibrosis, and the expression of Smad2 mRNA remained unchanged after bleomycin administration." (PMID 16438734, 2006). "Similarly, DST-3 significantly reduced the elevated p-Smad2/3 levels in BLM-induced pulmonary fibrosis in C57BL/6 mice." (PMID 41155944, 2025). "Furthermore, in vitro and in vivo experiments confirmed that PEA alleviated BLM-induced pulmonary fibrosis by inhibiting the TGF-β1/Smad2/3 signaling pathway and suppressing EMT." (PMID 40994978, 2025). "To investigate whether the ameliorative effect of TMEM176B on pulmonary fibrosis operates via the TGF-β-SMAD2/3 signaling, we utilized SB431542, an inhibitor of TGF-β." (PMID 39170226, 2024). "The TGF-β1 and Smad2 pathways play key roles in regulating pulmonary fibrosis." (PMID 38635081, 2024). "Promoted lung fibrosis through TGF-β-induced Smad2 (in vivo, in vitro)." (PMID 38745756, 2024). "Mechanism study found that MSCs supernatant could inhibit TGF-β1-induced phosphorylation of Smad2 and Smad3 to suppress the activation of pulmonary fibrosis cells." (PMID 37580529, 2023). "Treatment with the SIRT2 inhibitor AGK2 significantly attenuated the degree of pulmonary fibrosis and reduced the phosphorylation of Smad2/3; therefore, SIRT2 may be involved in IPF development by regulating the Smad2/3 pathway." (PMID 37483618, 2023). "Inhibition of SIRT2 alleviated fibroblasts activation and pulmonary fibrosis via Smad2/3 Pathway." (PMID 37483618, 2023). "In our study, treatment with CAT decreased Ang II and AT1 as well as TGF-β/Smad2/3, indicating that CAT may attenuate the progression of BLM-induced lung fibrosis in mice partly by inhibiting phosphorylation of Smad2/3 via decreasing Ang II expression." (PMID 35685407, 2022). "Furthermore, our findings demonstrated that NecroX-5 ameliorated BLM-induced pulmonary fibrosis by inhibiting the TGF-β1/Smad2/3-mediated EMT process, which is dependent on the inhibition of NLRP3 inflammasomes." (PMID 35596212, 2022). "ADAR1-p110 and ADAR1-p150 regulate the processing of the pri-miR-Let-7d and mature Let-7d in such a way that the sub-expression of the latter deregulated, in turn, the expression of COL3A1 and SMAD2, proteins involved in the development of idiopathic pulmonary fibrosis." (PMID 36012303, 2022). "TGF-β1 signal transduction can be activated via the translocation of Smad2/3 in pulmonary fibrosis." (PMID 36386240, 2022). "In conclusion, these changes indicated that BBJ could inhibit lung fibrosis through the TGF-β1/Smad2/3 pathway." (PMID 35418869, 2022). "TGF-β1/Smad2/3 was proven to be the upstream signaling pathway of lncITPF in pulmonary fibrosis." (PMID 36014574, 2022). "Thus, we inferred that NecroX-5 alleviated TGF-β1/Smad2/3 signalling medicated EMT process and pulmonary fibrosis associating with BLM by suppressing NLRP3 inflammasome activation." (PMID 35596212, 2022). "For example, SMAD3 is the main transcription factor for TGF-β1 signals and acting on TGF-β-mediated Smad2/3 signaling may prevent or treat pulmonary fibrosis in COVID-19-infected cases." (PMID 34539756, 2021). "As reported in previous researches, the inhibition of Smad2/3 signaling pathway could significantly attenuate the formation of scar tissue in central nervous system and pulmonary fibrosis." (PMID 34975478, 2021). "However, as both HCl- and NM-induced pulmonary fibrosis models exhibited a sex-related activation of canonical SMAD2 and SMAD3, suggesting that other isoforms of TGF-β are activated when mice are exposed to NM." (PMID 34072833, 2021). "Although the mechanism has not completely been clarified, alveolar epithelial damage, interstitial inflammation and transforming growth factor (TGF)-β/Smad2/3-mediated epithelial-mesenchymal transition (EMT) play a vital role in the pathogenesis of BLM-induced lung fibrosis." (PMID 33952237, 2021).
pulmonary fibrosis (continued). "Besides, SiNP-100 not only kept biological activities of TGF-β1 in binding cell receptors and triggering lung fibrosis, but also slowed degradation rate and prolonged activation of the TGF-β/Smad2 pathway which directly promotes lung fibrosis." (PMID 33869157, 2021). "Indeed, our study showed that pulmonary TGF-β/Smad2/3 signaling was activated during BLM-induced lung fibrosis." (PMID 31775746, 2019). "A previous report has shown that CTHRC1 plays a protective role in pulmonary fibrosis and tissue repair and may be clinically applied for treating fibrosis as it decreases collagen matrix deposition by inhibiting Smad2/3 activation." (PMID 31185973, 2019). "Finally, in mouse model of bleomycin-induced pulmonary fibrosis, therapeutic application of tannic acid resulted in a significant reduction of lung fibrosis, decrease in collagen-1 content and of Smad2 phosphorylation in the lungs." (PMID 31358001, 2019). "Moreover, vitamin D deficiency aggravated TGF-β/Smad2/3 activation and subsequent EMT during BLM-induced pulmonary fibrosis." (PMID 31775746, 2019). "However, activating Wnt/β-catenin signaling was required for TGF-β/Smad2/3 signaling during myofibroblast proliferation, suggesting that Wnt/β-catenin-activated TGF-β/Smad2/3 signaling in epithelial and mesenchymal cells contributed to lung fibrosis." (PMID 28588349, 2017). "The Smad2/3/4 complex moves to the nucleus and increases the transcription of extracellular matrix genes, thereby enhancing collagen and fibronectin synthesis in the extracellular matrix and promoting the development of pulmonary fibrosis." (PMID 28562330, 2017). "In the present study, we hypothesized that iPS cell transplantation could mitigate TGF-β1/Smad2/3 signaling pathway as well as EMT process during pulmonary fibrosis." (PMID 27895584, 2016). "Taken together, these findings suggest that iPS cells could inhibit BLM-activated TGF-β1/Smad2/3 signaling pathway in pulmonary fibrosis mice." (PMID 27895584, 2016). "In addition, as determined by luciferase assays and Western blotting, SMAD2, a crucial mediator of pulmonary fibrosis, was identified to be one of target genes of miR-486-5p." (PMID 26370615, 2015). "Studies have indicated that lung epithelial cell-specific loss of α3 integrin expression reduced EMT and protected from lung fibrosis, apparently by inhibiting tyrosine phosphorylation of β-catenin and formation of β-catenin/Smad2 complex, and it was confirmed in IPF patients." (PMID 23476100, 2013). "Moreover, the TGF-β/Smad2 axis is a strong driver for tissue damage, such as lung fibrosis." (PMID 35700140, 2022). "Thus, strategies to avoid these deleterious effects could involve inhibiting TGF-β signaling selectively in excessive activated lung fibroblasts, as TGF-β-triggered Smad2/3 signaling is pivotal in the induction of pulmonary fibrosis in animal models." (PMID 35355726, 2022). "Our results illustrated that Sirt2 possibly regulates Smad2/3 directly or indirectly and lead to higher phosphorylation of Smad2/3 in response to stimulators; Sirt2 may promote the activation of fibroblasts and the development of pulmonary fibrosis through Smad2/3 pathway." (PMID 34925016, 2021). "Our data connecting complement activation with fibrosis are in accordance with other disease model such as lung fibrosis where complement might lead to SMAD2/3 dependent and independent pathway activation, shifting the initial acute inflammatory response in a chronic profibrotic state." (PMID 29875766, 2018). "Because phosphorylation of Smad signaling by the activated TGFβ1 receptor I is a major step in the initiation of TGFβ1 signal transduction, we further examined whether Smad2 and Smad3 phosphorylation in bleomycin-induced pulmonary fibrosis was changed by AG treatment." (PMID 19552800, 2009).